APP (amyloid beta precursor protein)
Diseases named in the same sentence as APP in open-access papers (continued):
Sharing a sentence is not in itself a finding about the gene and the disease.
Cognitive impairment (continued). "These aberrant neuronal activity and/or seizure modulate cognitive deficits in amyloid precursor protein (APP) transgenic mice and patients with amnestic mild cognitive impairment, and may directly contribute to cognitive deficits early in AD progression." (PMID 29245901, 2017). "Moreover, we found that APP/PS1-ob/ob mice had a more severe cognitive impairment than observed in APP/PS1 mice at the age of 6 months through the action trajectory in the MWM test and behavior in the nest building experiment." (PMID 28467789, 2017). "In this study, we hypothesised that both cerebral and systemic microvascular pathologies exist in 4- to 5-month-old male APPswe/PS1dE9 (APP/PS1) transgenic mice prior to the onset of cognitive impairment." (PMID 28741167, 2017). "The typical behavior defect of APP/PS1 mice is cognitive impairment." (PMID 28931427, 2017). "Additionally, reduction of endogenous tau was shown to ameliorate network hyperexcitability and cognitive impairment in transgenic APP mice." (PMID 28392767, 2017). "Our results provide evidence that BJJS relieved the cognitive impairment in APP/PS1 mice." (PMID 29190943, 2017). "Altogether, our data suggest the presence of cognitive impairment both in AD (APP/PS1-Sham) and diabetic (Wt-STZ) mice, with a synergistic effect in APP/PS1-STZ mice, supporting a cross-talk between both pathology types that worsens episodic and spatial memory." (PMID 26156287, 2016). "Importantly, NO2 aggravated cognitive impairment, amyloid deposition, neuroinflammation and neurodegeneration in APP/PS1 model mice." (PMID 26928013, 2016). "In recent years the main focus of AD research has been on the amyloid hypothesis, which postulates that extracellular precipitates of beta amyloid (Aβ) derived from amyloid precursor protein (APP) are responsible for the cognitive impairment seen in AD." (PMID 27530256, 2016). "Data obtained in the fly support the hypothesis that APP acts as a transmembrane receptor, and that disruption of its normal function may contribute to cognitive impairment during early AD." (PMID 28008309, 2016). "Results showed that the NIM network underlying cognitive impairment of SAMP8 mice contained 127 nodes and 178 edges with characteristic path length 3.964 (Figure 3a3), and network of APP/PS1 mice contained 67 nodes and 84 edges with characteristic path length 6.533 (Figure 3b3)." (PMID 27049828, 2016). "APP transgenic mouse models of AD that are devoid of BACE1 expression via BACE1 gene knockout (BACE1−/− mice) fail to generate Aβ and lack the amyloid plaques and cognitive impairments found in APP transgenic mice that express both BACE1 alleles." (PMID 25567526, 2015). "Although increased APP expression in the hippocampus of AD model rats was not significantly reduced, cognitive impairment, PP2A downregulation and neuronal loss and apoptosis were alleviated by TGF-β1 post-treatment via IN." (PMID 25658940, 2015). "Additionally, recent work has shown that TNF-α inhibitors can reduce Aβ-plaques and phosphorylation of tau protein in APP/PS1 mice and 3xTg mice, as well as ameliorate cognitive deficits associated with chronic inflammation." (PMID 26340637, 2015). "Our working hypothesis claimed that BDNF deficiency should accelerate the onset of cognitive impairment and amplify the cognitive deficits displayed by the APP/PS1-mice." (PMID 25852506, 2015). "These APP/PS1 mice are known to have cognitive deficits as well, which might contribute to the observed increased anxiety." (PMID 26379542, 2015). "This further exacerbates synaptic and cognitive impairments in APP/PS1 mice." (PMID 26526066, 2015). "Use of pharmacological inhibitors of γ-secretase (GSI) and β-secretase (BSI) indicate that a metabolite of APP other than Aβ may be responsible for the cognitive deficits in FDDKI mice." (PMID 26405694, 2015). "Cognitive impairment, however, cannot be observed in the APP/PS1 mice until 8 months of age." (PMID 25101849, 2014).
Cognitive impairment (continued). "This sudden activation of APP metabolism occurs at a prodromal-like phase of the pathology, where the first cognitive deficits are observed in 5xFAD males tested in a hippocampal-dependent olfactory task, and it is maintained over the symptomatic phase (6 months)." (PMID 25278878, 2014). "In addition, the APP/PS1 KI mouse shows an age-dependent development of cognitive deficits in two different memory domains relevant to AD: spatial reference memory and recognition memory." (PMID 23705774, 2013). "Here we report that BRI2-Aβ mice, including the BRI2-Aβ1-42 mice show a surprising lack of cognitive impairment; a finding that may have implications regarding the mechanisms by which mice overexpressing mutant APP develop cognitive deficits." (PMID 23663320, 2013). "Thus, the relative contribution of Aβ and/or other APP metabolites to cognitive deficits in the APP over-expression models is challenging to resolve." (PMID 23663320, 2013). "In conclusion we have demonstrated that 100 cGy of 56Fe particle radiation can cause cognitive impairment as well as increased Aβ plaque pathology in APP/PS1 mice, without clear changes in glial activation." (PMID 23300905, 2012). "Therefore JWH, the CB2 selective agonist, was capable of improving cognitive impairment and of reversing the reduction in 18FDG uptake in cortical areas and hippocampus of Tg APP." (PMID 22248049, 2012). "First we examined whether continuous oral treatment with a low dose (0.2 mg/kg/day for 4 months) of cannabinoids was able to rescue the cognitive impairment of Tg APP eleven months old mice in the novel object recognition test." (PMID 22248049, 2012). "Interactions between HSA21-associated S100B and amyloid precursor protein (APP) might effect neural progenitor development and contribute to the cognitive impairment in DS." (PMID 21779383, 2011). "In addition a recent study has shown that expression of PrPC is required for the manifestation of cognitive deficits in an APP/PS1 Tg mouse model of AD, as determined by Morris water maze testing." (PMID 20946660, 2010). "Moreover, metabolites of cerebellar neurons significantly reduced brain Aβ levels and reversed cognitive impairments and other AD-like phenotypes of APP/PS1 transgenic mice, in both early and late stages of AD pathology." (PMID 19436731, 2009). "However, the APP/PS1 mice only showed cognitive impairments." (PMID 40344642, 2025). "Therefore, this study aimed to investigate whether DSS and its disassembled prescriptions (QDW and DW) improve cognitive deficits in APP/PS1 mice and elucidate the role of gut microbiota modulation in this process." (PMID 40822397, 2025). "None of the cases with APP variants exhibited dementia or cognitive impairment." (PMID 39867380, 2025). "Moreover, our previous study found that MGO reduced the number of cells in the hippocampus formation, such as cornu ammonis 1 (CA1), CA3, and dentate gyrus (DG) and induced the accumulation of APP and Aβ to increase depression-like and cognitive impairment behaviors." (PMID 40362855, 2025). "Patients suffering from familial AD (fAD) develop cognitive impairment and dementia between 50 and 65 years and bear mutations in one of the three genes involved in the β-amyloidogenic pathway: APP, presenilin 1 (PSEN1), and presenilin 2 (PSEN2); increased APP dosage is also causative of AD and CAA." (PMID 39475348, 2024). "To examine if PPARδ agonist 5a could alleviate AD-like pathology based on its anti-inflammatory properties, we investigated the therapeutic efficacy of 5a using mice with scopolamine-induced cognitive impairment and 12-month-old APPswe/PSEN1dE9 (APP/PS1) double transgenic mice." (PMID 39431021, 2024). "Similarly another study identified METTL3 gene (encoding the subunit of N6-adenosine-methyltransferase) confers protection against mitochondrial dysfunction and cognitive impairment in APP/PS1 transgenic mice by upregulating Mfn2 via N6-methyladenosine modification." (PMID 39122453, 2024).
Cognitive impairment (continued). "Interestingly, our experiments demonstrated that KXS could alleviate neuroinflammation mediated by NLRP3 inflammasome activation which improved cognitive impairment in APP/PS1 mice." (PMID 36918872, 2023). "Moreover, we tested whether ELS enhanced cognitive impairments in APP/PS1 mice specifically, and if cognitive performance correlated with hippocampal synaptosomal protein content." (PMID 37980670, 2023). "Osaka mutation (APP E693Δ) is the deletion of codon 693 of APP gene, resulting in mutant Aβ lacking the 22nd glutamate, which accelerates Aβ oligomerization without forming amyloid fibrils and disrupts synaptic function to cause cognitive impairment in humans." (PMID 37589021, 2023). "Notably, oral administration of C3G alleviated cognitive deficits in APP/PS1 mice." (PMID 37408220, 2023). "To determine whether apoE has isoform-dependent effects on hAPP/Aβ-induced behavioral alterations and cognitive impairments in adult female and male mice at 6 months of age, we crossed APP NL-G-F mice with E2, E3, and E4 mice to generate NL-G-F/E2, NL-G-F/E3, and NL-G-F/E4 mice." (PMID 35299942, 2022). "Thus, a prenatal immune challenge is sufficient to trigger a series of neuropathologic events that lead to a slow but gradual increase in amyloidogenic APP processing and cognitive impairments, potentially representing a state of increased vulnerability of the brain to AD." (PMID 35682823, 2022). "The mouse model APP/PS1ΔE9 that expresses APP with the Swedish mutation and mutant human PSEN1 with a deletion of exon 9 shows formation of amyloid plaques prior to typical cognitive impairments, is used to examine pathophysiological events associated to preclinical AD." (PMID 35011699, 2022). "To determine whether apoE has isoform-dependent effects on hAPP/Aβ-induced behavioral alterations and cognitive impairments in aged female and male mice at 18 months of age, we crossed APP NL-F KI with E2, E3, and E4 mice to generate NL-F/E2, NL-F/E3, and NL-F/E4 mice." (PMID 35299942, 2022). "Recently, Stańczykiewicz and colleagues have shown that ovocystatin has beneficial properties for cognitive functions in young rats, and might prevent aging-related cognitive impairment in older animals as well as reduce memory decline in the APP/PS1 mice model." (PMID 35566501, 2022). "However, it is unknown whether RH similarly promotes the development of cognitive deficits in diabetic APP/PS1 (APP/PS1-DM) mice." (PMID 35077394, 2022). "Because the expression of LIMK1 is restricted to the hippocampal excitatory neurons, our results reveal that increased cofilin activity in hippocampal excitatory neurons may be particularly important for early synaptic and cognitive deficits in APP/PS1 transgenic mice." (PMID 34315506, 2021). "Further mechanistic insight into how APN deficiency aggravated AD pathology and cognitive impairment found that the dysregulation of APN signaling did not alter APP expression and processing, indicating that APN signaling had no pronounced effect on Aβ generation." (PMID 34775673, 2021). "Therefore, this study aimed to verify whether autophagic stress induces neuron apoptosis and cognitive impairment in APP/PS1 mice in response to sevoflurane treatment, and to explore the underlying mechanism." (PMID 32385796, 2021). "The “GSK3 hypothesis in AD” suggests that the overactivation of GSK-3β is closely related to several features of the pathology of AD, including microglia-mediated inflammation, Aβ production, APP processing, tau phosphorylation, neuronal death, and cognitive deficits." (PMID 32714487, 2020). "Indeed, chemogenetic inhibition of hippocampal PV interneurons during MWM learning rescued learning and memory impairments in APP/PS1-PV-Cre mice at 15–17 weeks of age, confirming that hyperexcitable PV interneurons are causally involved in the observed cognitive deficits at this age." (PMID 31431685, 2020).
Cognitive impairment (continued). "Since it is well-known that neuronal degeneration and loss is widely considered as the main contributors to cognitive impairment in AD, to assess whether tan IIA can attenuate neuronal loss, we measured the change in the number of NeuN-positive neurons in the brain of APP/PS1 mice." (PMID 33054814, 2020). "NLRP3 or caspase-1 deficiency in APP/PS1 mice leads to reduced brain caspase-1 and IL-1β activation, increased microglial Aβ phagocytosis, reduced brain Aβ load, and protection of neuronal spine loss, long-term potentiation (LTP) decline, and cognitive deficits." (PMID 32391019, 2020). "In this study, through taking advantage of transgenic APP/PS1 mice, a murine AD model, we show an ameliorating effect of miR-181a on cognitive deficits, which may relate to the retarded pericyte loss and blood-brain barrier breakdown via a negative regulation of pericyte apoptosis." (PMID 31467256, 2019). "Thus, to examine the effects of DISC1‐mediated mitophagy on cognitive deficits, we injected AAV8 encoding DISC1 in the hippocampus of APP/PS1 transgenic mice at 8 months old of age, when these mice already harbored extensive accumulation of amyloid plaques in the brains." (PMID 30488644, 2019). "Transgenic APP models allow for the analysis of chronic Aβ exposure and brain accumulation that could lead to a better understanding of the emergence and progression of cognitive impairment in AD." (PMID 30795807, 2019). "To examine whether overexpression of DISC1 ameliorates cognitive deficits through enhancing mitophagy, we injected bilaterally AAV8 encoding either DISC1, muFSFI, or GFP into the hippocampus of 8‐month‐old APP/PS1 transgenic mice and performed behavioral tests 4 months after injection." (PMID 30488644, 2019). "Importantly, SNX8 overexpression rescued cognitive impairment in APP/PS1 mice." (PMID 31551717, 2019). "Thus, our mature-onset data show that in APP/tTA mice, synaptic and cognitive deficits appear progressively: synaptic plasticity and spatial working memory are first affected, and then impairment of basal synaptic transmission and spatial reference memory emerge later." (PMID 30795807, 2019). "We then asked whether miR-181a affects cognitive deficits in APP/PS1 mice." (PMID 31467256, 2019). "The diversification of GO terms in APP mice to include ion transport, glutamate receptor signaling, and regulation of membrane potential was striking given the recurrent seizures exhibited by both AD patients and mouse models, as well as the critical role that seizures play in cognitive deficits." (PMID 29408867, 2018). "However, viral knockdown of neuronal BDNF in the hippocampus of APP/PS1 mice (in the absence of BFCN loss) neither increased the level of Aβ nor caused cognitive deficits." (PMID 29520217, 2018). "APP/PS1 transgenic mice, which overexpress the Swedish mutation of human amyloid precursor protein (APP) together with human presenilin-1 (PS1) deleted in exon 9, have shown cognitive deficits, Aβ deposits and cholinergic nerve degeneration mimicking AD pathology." (PMID 30237878, 2018). "Therefore, BJJS reduced toxic aggregation of Aβ may be the basis for mitigating the cognitive impairment in APP/PS1 mice." (PMID 29190943, 2017). "Thus, we propose that the suppression of hippocampal GSK-3β phosphorylation induced by the SM70EE-enhanced BDNF/PI3K/Akt signaling pathway contributes to the inhibition of APP processing by downregulating BACE1 to ameliorate the cognitive disorders induced by an I.C.V. injection of Aβ1–42." (PMID 29137190, 2017). "Our project intended to use behavior, molecular biology, morphology and other techniques to further investigate the hypothesis that aberrant calcium signaling pathways induced by a chronic diabetic state might exacerbate AD neuropathology and cognitive deficits in APP/PS1-ob/ob mice." (PMID 28467789, 2017).
Cognitive impairment (continued). "Previously, we created an HFSTZ APP/PS1 animal model, which displayed diabesity and hepatic steatosis; elevated peripheral Aβ level; enhanced Aβ level, plaque burden, astrocyte activation, vascular inflammation, glucose hypometabolism in the cerebrum, and caused cognitive impairment in APP/PS1 mice." (PMID 29258283, 2017). "Furthermore, systemic administration of LPS has been contributed to result in increased APP processing by β-secretase and intracellular accumulation of Aβ as well as cognitive impairment since LPS induces amyloidogenesis with concomitant increased neuroinflammation and oxidative damages." (PMID 28489589, 2017). "In particular, it has been demonstrated that soluble APPα regulates neural progenitor cell proliferation and that miscleavage of APP could greatly influence in developmental and postnatal neurogenesis, which could contribute to symptomatic cognitive deficits in AD." (PMID 27303258, 2016). "Thus, miscleavage of APP would readily influence on developmental and postnatal neurogenesis, which could contribute to cognitive deficits characterizing AD." (PMID 27303258, 2016). "However, there is no study performed to evaluate whether EGCG treatment ameliorates cognitive deficits in APP/PS1 transgenic mice and, if it does, whether the ameliorating effect is through regulating the balance of TrkA/p75NTR signaling." (PMID 24356899, 2014). "In addition, future studies are needed to better understand how “hunger” without reduced consumption of calories might delay the onset of Aβ pathology and cognitive deficits in APP or APP/PS1 mice and possibly block or delay the onset of AD." (PMID 23565247, 2013). "Interestingly this compound effectively counteracted the cognitive impairment of Tg APP mice." (PMID 22248049, 2012). "APP and APP/PS1 transgenic mice express high levels of amyloid beta (Aβ) and progressively develop many of the pathological phenotypes of AD, including abundant extracellular Aβ plaques, synaptic dysfunction and loss, astrocytosis, activation of microglia, and cognitive deficits." (PMID 22203915, 2012). "In this study, we utilized APPswe/PS1dE9 (APP/PS1) mice of different ages and first demonstrated that cerebral microvascular dysfunction occurs prior to cognitive impairment." (PMID 41367129, 2025). "Some studies have shown that enhancing the expression or activity of SIRT3 can improve mitophagy in APP/PS1 transgenic mice, alleviating synaptic damage and cognitive deficits." (PMID 40125832, 2025). "In a follow-up study, the same group reported that the CCK analogue ameliorated cognitive deficits and regulated mitochondrial dynamics by activating the CCKB receptor and the AMPK/Drp1 pathway in APP/PS1 mice." (PMID 40013092, 2025). "The convergence of genetic susceptibility and environmental exposures, such as the APOE gene and the Amyloid Precursor Protein (APP), along with lifestyle and nutritional status, further complicates the relationship between sarcopenia and cognitive disorders." (PMID 40435122, 2025). "Sildenafil decreases α-synuclein levels and oxidative stress in rats with aluminium-induced cognitive impairment and rescues protein kinase B/phosphorylated cAMP response element-binding protein (PKG/pCREB) signalling in APP/PS1 transgenic mice." (PMID 41250235, 2025). "In this study, we investigated the effects of C. tubulosa glycosides on cognitive function and AD pathology in APPswe/PS1dE9 double-transgenic (APP/PS1) mice, a well-established model characterized by Aβ deposition and cognitive deficits." (PMID 40860878, 2025). "In APP/PS1 mice, which develop AD pathology and cognitive impairments, TMF treatment significantly improved memory and reduced anxiety-related behaviors." (PMID 39997198, 2025). "Collectively, the results from Morris Water Maze indicate that 6-month-old APP/PS1 mice exhibit deficits in spatial learning and memory abilities, while the three-month treadmill exercise effectively improves these cognitive deficits." (PMID 41488046, 2025).